UFL1 (UFM1 specific ligase 1)
Diseases named in the same sentence as UFL1 in open-access papers (continued):
Sharing a sentence is not in itself a finding about the gene and the disease.
Down syndrome (1 paper, 2023). "Interestingly, UFM1, UFL1, and CDK5RAP3 are all key components of the UFMylation pathway which is an ubiquitin-like posttranslational protein modification, while TTC3 is an E3 ubiquitin ligase highly expressed in the CNS and is closely involved in Down syndrome." (PMID 36917672, 2023).
endotoxemia (1 paper, 2025). "It is further demonstrated that myeloid cell‐specific Ufl1 or Ufm1 deficiency in mice significantly alleviated inflammatory responses and tissue damage following lipopolysaccharide (LPS)‐induced endotoxemia and alum‐induced peritonitis." (PMID 39985286, 2025). "Deficiency of Ufl1 or Ufm1 in mice shows a significantly attenuated inflammatory response in LPS‐induced endotoxemia, alum‐induced peritonitis and E. Coli‐induced sepsis." (PMID 39985286, 2025). "Myeloid cell‐specific deletion of Ufl1 or ubiquitin‐fold modifier 1 (Ufm1) significantly alleviates inflammatory responses in LPS‐induced endotoxemia and alum‐induced peritonitis." (PMID 39985286, 2025).
glioblastoma (1 paper, 2022). The most malignant astrocytic tumor (WHO grade IV). "When we performed immunoprecipitation experiments with membranous fractions from glioblastoma T98G cells, we likewise detected complexes comprising UFL1, C53, and γ-tubulin, indicating that these protein complexes are not limited to U2OS cells." (PMID 35159364, 2022).
liver disease (1 paper, 2023). "To determine whether Ufl1 or Ufbp1 depletion-mediated liver injury is associated with liver disease, we examined the expression of known implicated components in our models." (PMID 37131258, 2023). "In summary, Ufl1/Ufbp1 provides a potential druggable target for treating liver disease in humans." (PMID 37131258, 2023).
lymph node metastasis (1 paper, 2026). "Clinicopathological correlation analysis further showed that high RASSF1C expression was associated with poor differentiation and advanced TNM stage, whereas low UFL1 and IRF7 expression was associated with lymph node metastasis." (PMID 41912489, 2026).
microcephaly (1 paper, 2025). A congenital or acquired developmental disorder in which the circumference of the head is smaller than normal for the person's age and sex. "Insufficient UFL1 and UFBP1 levels resulted in UFMylation defects in CYB5R3, thereby promoting microcephaly." (PMID 39757643, 2025). "UFL1 and UFBP1 were confirmed to play a crucial role in the survival of mouse neurons, as the UFL1 and UFBP1 knockout in mice led to a significant decrease in brain protein levels, increased neuronal cell death in the cortex and hippocampus, ultimately resulting in microcephaly." (PMID 39757643, 2025).
osteosarcoma (1 paper, 2022). A usually aggressive malignant bone-forming mesenchymal neoplasm, predominantly affecting adolescents and young adults. "To ascertain whether membranous UFL1 associates both with C53 and γTuRC proteins in different cell types, we first performed immunoprecipitation experiments with extracts from the crude membranous fraction (P2) from human osteosarcoma U2OS cells." (PMID 35159364, 2022). "Knockout of UFL1 or C53 in human osteosarcoma cells induces ER stress and boosts centrosomal microtubule nucleation accompanied by γ-tubulin accumulation, microtubule formation, and ER expansion." (PMID 35159364, 2022).
pancreatic cancer (1 paper, 2023). "In this study, the ufmylation of RPL10 was confirmed in the tissues of PAAD patients and pancreatic cancer cell lines, and this modification was mediated by UFL1 at specific sites and cleaved by UFSP2." (PMID 37280198, 2023). "Therefore, we knocked down E3 ligase UFL1 to evaluate the changes of RPL10 ufmylation, proliferation and stemness-related characteristic features in pancreatic cancer cells." (PMID 37280198, 2023). "To elucidate the process of RPL10 ufmylation involved in pancreatic cancer cells, we used immunoprecipitation to examine the interactions between co-substrates RPL10 and UFM1 as well as between RPL10 and E3 ligase UFL1, which could be similar to the ufmylating modifications of ASC1 and RPL26." (PMID 37280198, 2023).
pancreatic ductal adenocarcinoma (1 paper, 2026). An infiltrating adenocarcinoma that arises from the epithelial cells of the pancreas. "Moreover, immunohistochemical (IHC) validation using tissue microarrays from 20 human pancreatic ductal adenocarcinoma (PDAC) specimens revealed that the overall expression of RASSF1C and hypoxia-inducible factor-1 alpha (HIF-1α) was higher than that of UFL1 and IRF7." (PMID 41912489, 2026).
peritonitis (1 paper, 2025). Inflammation of the peritoneum (tissue that lines the abdominal wall and covers most of the organs in the abdomen). "We also analyzed the role of Ufl1 in NLRP3 inflammasome‐driven peritonitis by i.p. injection of Alum." (PMID 39985286, 2025).
prostate tumors (1 paper, 2026). "This study reveals that UFL1 is dysregulated in ENZ-resistant cells, xenograft models, and prostate tumors." (PMID 41608626, 2026).
renal cell carcinoma (1 paper, 2023).
viral infection (1 paper, 2023). "In this study, we identified UFL1 as a viral infection regulated protein which can promote antiviral innate immunity independent of UFMylation." (PMID 35871231, 2023). "According to our results, the mechanism of UFL1 down-regulation after viral infection might related to TLRs triggered NF-κB pathway." (PMID 35871231, 2023). "Viral infection could dysregulate the UFL1 expression, thus promoted STING degradation by TRIM29 to prevent excessive production of IFN." (PMID 35871231, 2023).
ZIKV infection (1 paper, 2025). "As no commercial antibodies are available for the orthoflaviviral NS2A protein, we sought to validate the interaction of UFL1 and NS2A during ZIKV infection using a ZIKVFlag-NS2A-expressing virus." (PMID 40459261, 2025). "However, during ZIKV infection, we found that NS3, but not capsid, interacted with UFL1." (PMID 40459261, 2025).
tumor (17 papers, 2011 to 2025). "Similar to PD-1 blockade, mice with UFL1 deficient T cells exhibit anti-tumour effects, including significantly reduced PD-1 levels and enhanced T-cell immune responses." (PMID 41179291, 2025). "Recently, one study demonstrated that ablation of UFL1 in T cells inhibited PD-1 UFMylation to increase anti-tumor immunity." (PMID 39247188, 2024). "A conditional knockout of UFL1 in vivo led to slower tumour growth in comparison with wild‐type mice, suggesting that the deletion of UFL1 increases T‐cell activity within the tumour, and leads to a more robust anti‐tumour response." (PMID 39259506, 2024). "Through single-cell RNA sequencing, an increase in tumor-infiltrating cytotoxic CD8+ T cells was observed in these UFL1 conditional knockout (cKO) mice." (PMID 38638430, 2024). "This study investigated the physiological role of UFMylation in T cells by examining mice with a conditional knockout (cKO) of Ufl1, focusing on tumor immunity." (PMID 39247188, 2024). "Tumor sizes of UFL1 knockdown were significantly smaller than control group with the decrease of RPL10 ufmylation in tumor tissues." (PMID 37280198, 2023). "Coincidently, the Ki67 staining showed a decline of tumor growth with UFL1 knockdown compared to NC group." (PMID 37280198, 2023). "The ligating enzyme, Ufl1, was shown to interact with CDK5Rap3, a tumor suppressor that regulates the cyclin D1 synthase." (PMID 24921187, 2014). "Accordingly, Ufl1 was reported to be decreased in several tumor tissues and increased in cells lines, with little cell invasion." (PMID 24921187, 2014). "Therefore, UFL1 is a potential immune-enhancing target that warrants further exploration in tumor immunotherapy." (PMID 41179291, 2025). "Ablation of UFL1 in T cells inhibited PD-1 UFMylation to increase anti-tumor immunity." (PMID 39247188, 2024). "Consequently, the ablation of UFL1 in T cells diminishes PD-1 stability, promoting a robust anti-tumor immune response." (PMID 39247188, 2024). "Thus, UFL1 seems to have two opposite functions: one in tumor suppression and the other in tumor development, perhaps depending on its target proteins for ufmylation in different types of cells and tissues." (PMID 25852645, 2015). "Thus, UFBP1, like UFL1, plays two opposite roles as a tumor suppressor by inhibiting NF-κB signaling and as a tumor promoter by serving as a cofactor of the UFM1-conjugating system for ASC1 in development of breast cancer." (PMID 25852645, 2015). "Moreover, we uncover a novel regulatory role of LRP1, especially its β‐chain, in modulating the association between UFL1 and OGA to maintain OGA stability and exert tumor‐suppressing activity by abating NF‐κB O‐GlcNAcylation and inhibiting its downstream signaling pathway." (PMID 39405202, 2024). "In addition, UFL1 was shown to cooperate with LZAP in suppression of cell invasion and NF-κB signaling by mutual stabilization, suggesting that UFL1 may act as a tumor suppressor." (PMID 25852645, 2015). "When tumor tissues were analyzed, the level of ufmylated RPL10 was markedly decreased from UFL1 knockdown, along with the decline of KLF4." (PMID 37280198, 2023).
tumor (continued). "Recent studies indicate that DDRGK1 interacts with a protein complex containing UFL1 (UFM1-specific ligase 1), the putative tumor suppressor LZAP/C53 and UFM1 (ubiquitin fold modifier 1), and both UFL1 and LZAP/C53 have a regulatory role in the NF-κB pathway." (PMID 23675531, 2013). "The absence of UFL1 results in reduced PD-1 UFMylation in T cells, contributing to the PD-1 degradation, which enhances T cell anti-tumor function." (PMID 41179291, 2025). "Mice lacking the UFMylation E3 ligase UFL1 specifically in T cells demonstrated superior tumor suppression." (PMID 38638430, 2024). "Interestingly, UFL1 can be phosphorylated by AMP-activated protein kinase (AMPK), which leads to the reduction in PD-1 UFMylation and the subsequent destabilization of PD-1, consequently enhancing CD8+ T cell activation and anti-tumor immunity." (PMID 39858578, 2024). "However, this study found that HNK has a definite relationship with UFL1 and BRE1B and can promote the combination of UFL1 and BRE1B with HIF-1α, which improves the ubiquitination degradation level of HIF-1α to a certain extent, and then reverses tumor growth via the glycolytic pathway." (PMID 35350760, 2022). "Single‐cell sequencing data indicated that absence of UFL1 in T cells increased the infiltration of cytotoxic CD8+ T cells, consistent with the observed enhanced anti‐tumour effect." (PMID 39259506, 2024).
cancer (12 papers, 2019 to 2025). A tumor composed of atypical neoplastic, often pleomorphic cells that invade other tissues. "As such, UFL1 can be considered a biomarker of BRCA1-deficient cancer cells and thus indicate the likely response to chemotherapy." (PMID 38657865, 2024). "H&E staining of liver sections from mice revealed extensive hepatocyte ballooning and cytoplasmic vacuolization, inflammatory cell infiltration, areas of necrosis, and cancer nodules after DEN induction or Ufl1 loss." (PMID 37131258, 2023). "The IdU track length in siUFL1 cells was ~50% shorter than in negative control (siNC) cells, while UFL1 re-expression fully reversed this defect in three UFL1-depleted cancer cell lines (Fig. EV1I)." (PMID 40940420, 2025). "This study not only clarify the significant role of UFMylation in T-cell function but also position UFL1 as a promising target for cancer therapy." (PMID 39247188, 2024). "Additionally, a reduction in UFL1 expression was observed across multiple cancers." (PMID 39247188, 2024). "Amplification, deletion or mutation of genes encoding the UFMylation factors (UBA5, UFC1, UFL1, UfSP2 and UFM1) has been detected in malignant tumors from various tissues and organs in the TCGA database, indicating that UFMylation may promote or suppress tumorigenesis in different cellular contexts." (PMID 30783677, 2019). "Disrupting PD-L1 UFMylation through the silencing of UFL1 or UFM1 resulted in PD-L1 stabilization in a variety of human and mouse cancer cell lines, which weakened antitumor immunity both in vitro and in mouse models." (PMID 38638430, 2024). "Disrupting PD-L1 UFMylation through the depletion of UFL1 or UFM1, or by defective UFMylation of PD-L1 itself, stabilized PD-L1 in various human and murine cancer cell lines, which impair antitumor immunity both in vitro and in vivo." (PMID 39247188, 2024). "Inhibiting PD-L1 UFMylation by silencing UFL1 or UFM1, or by the defective UFMylation of PD-L1, stabilized PD-L1 in multiple human and murine cancer cells and undermined antitumor immunity both in vitro and in mice." (PMID 37947621, 2023). "A comprehensive analysis of genomic alterations in the eight UFMylation family genes (UFM1, UBA5, UFC1, UFL1, UfBP1, CDK5RAP3, UfSP1, and UfSP2) across the TCGA database of 33 cancer types identified 55 recurrent and focal somatic copy number alteration events in UFMylation family genes." (PMID 37947621, 2023). "Therefore, we speculate that UFL1 and BRE1B are also E3 ligases involved in the ubiquitination degradation of HIF-1α, while HNK promotes the ubiquitination degradation of HIF-1α protein by UFL1 and BRE1B in cancer cells." (PMID 35350760, 2022).
infection (4 papers, 2022 to 2025). The state of being infected such as from the introduction of a foreign agent such as serum, vaccine, antigenic substance or organism. "We observed a strong decrease in zebrafish larvae survival during infection upon depletion of ufm1 and ufl1, both in the case of S. flexneri and S. Typhimurium." (PMID 40501833, 2025). "Together, we show that our proximity biotinylation approach is effective to identify novel host factors in close proximity to S. flexneri during infection, including UFL1 and other E3 ligases." (PMID 40501833, 2025). "Additionally, we find that UFL1 promotes infection of several orthoflaviviruses, including DENV, ZIKV, WNV, and YFV, but it does not regulate infection by the hepacivirus, hepatitis C virus (HCV)." (PMID 40459261, 2025). "The limited UFM1 decoration of S. flexneri during infection led us to hypothesise that additional bacterial effectors may intersect with the UFMylation cascade beyond UFL1 recruitment." (PMID 40501833, 2025). "In addition, we used infection with lentiviral particle suspensions to knock down and overexpress UFL1 in ovaries and GCs, respectively." (PMID 35610622, 2022). "However, depletion of UFL1 did reduce the levels of ZIKV-GLuc in the 24–72 h after infection." (PMID 40459261, 2025). "Microscopy experiments validated the localisation of UFL1 and UFM1 to the surface of S. flexneri during infection in HeLa cells, using both HA-tagged exogenous expression and antibodies against the endogenous proteins." (PMID 40501833, 2025). "In both cases, UFL1 and UFM1 localised to S. flexneri, suggesting a broad and conserved role during infection." (PMID 40501833, 2025). "Together, these data show that UFL1 interacts with specific DENV and ZIKV proteins during infection." (PMID 40459261, 2025). "We found that compared to cells treated with control non-targeting siRNA, depletion of UFL1 decreased the levels of infectious DENV in the supernatant at 48 h post-infection, as measured by focus-forming assay (FFA) (left)." (PMID 40459261, 2025). "We observed that UFL1 and UFM1 were also recruited to the surface of S. Typhimurium at 3 hours post infection, indicating that bacterial UFMylation is not a phenotype exclusive to S. flexneri." (PMID 40501833, 2025). "Our work has shown that both UFL1 and its substrate peptide UFM1 are recruited to the surface of S. flexneri and S. Typhimurium during infection, which showed little to no overlap with bacterial ubiquitylation." (PMID 40501833, 2025). "While deletion of ipaH9.8 did not affect UFL1 recruitment to S. flexneri, we observed a higher decoration of UFM1 in S. flexneri ΔipaH9.8 compared to WT at 3 hours post infection (2.6 ± 0.5-fold), which further increased (4.4 ± 0.6-fold) in the case of the double mutant ΔrfaCΔipaH9.8." (PMID 40501833, 2025).
UFL1 also shares sentences with these, for which no sentence is quoted: atherosclerosis (1 paper); Cirrhosis (1); Cluster headache (1); Crohn disease (1); Hip dysplasia (1); Infertility (1); ischemic heart diseases (1); lymphoid neoplasm (1); myeloid leukemia (1); pancreatic adenocarcinoma (1); schizophrenia (1).